MYNN (myoneurin)
Synonyms: OSZF; ZBTB31; SBBIZ1; ZNF902
Tractability: PROTAC: ubiquitination databases record sites on it.
Gene: Protein-coding gene on chromosome 3 (169,773,377 to 169,789,716, forward strand). Ensembl gene ENSG00000085274.
Subcellular location: Nucleus
Subcellular location (Human Protein Atlas): Nucleoplasm
Gene Ontology:
Molecular function: protein binding; DNA-binding transcription factor activity, RNA polymerase II-specific; RNA polymerase II cis-regulatory region sequence-specific DNA binding
Biological process: regulation of transcription by RNA polymerase II
Cellular component: nucleoplasm; nucleus
Genetic constraint (gnomAD): Loss-of-function variants: 18 observed, 48.24 expected, observed/expected ratio (o/e) 0.37, 90% interval 0.26 to 0.55. The upper end of that interval is the gene's LOEUF score, 0.55, which puts it in group 2 of 6, group 1 being the genes least tolerant of losing a copy. Missense variants: 506 observed, 682.13 expected, observed/expected ratio (o/e) 0.74, 90% interval 0.69 to 0.8. Synonymous variants: 220 observed, 244.54 expected, observed/expected ratio (o/e) 0.9, 90% interval 0.81 to 1.01.
Homologues: Orthologues: chimpanzee MYNN (100% identical), macaque MYNN (97% identical), rabbit MYNN (97% identical), dog MYNN (96% identical), guinea pig MYNN (96% identical), pig MYNN (95% identical), rat Mynn (93% identical), mouse Mynn (92% identical), tropical clawed frog mynn (62% identical). Paralogues in human: ZNF214 (22% identical), ZNF34 (22% identical), ZNF285 (22% identical), ZNF333 (22% identical), ZNF407 (22% identical), ZKSCAN7 (21% identical), ZNF572 (21% identical), ZNF136 (21% identical), ZNF287 (21% identical), ZNF852 (21% identical), ZNF527 (21% identical), ZNF627 (21% identical), and 38 more.
Diseases named in the same sentence as MYNN in open-access papers:
MYNN is named in the same sentence as 7 diseases in open-access papers, as found by Europe PMC text mining. Sharing a sentence is not in itself a finding about the gene and the disease. The quoted sentences say what the papers report.
bladder cancer (2 papers, 2024). "MYNN also exhibited heightened activity, resulting in an enhanced susceptibility to colorectal cancer and bladder cancer." (PMID 39187937, 2024). "GWAS Catalog has revealed that a non-synonymous polymorphism (rs10936599) at chromosome 3q, covering the MYNN gene, is correlated with colorectal cancer, telomere length, multiple myeloma, bladder cancer, and so on." (PMID 38165846, 2024). "Moreover, there may be a significant correlation between the polymorphisms for Telomerase RNA Component (TERC) (rs2293607) and MYNN (rs10936599), which is responsible for elevated risk of colorectal cancer, colorectal adenomas, and bladder cancer." (PMID 38165846, 2024).
ovarian carcinoma (2 papers, 2009 to 2010). A malignant neoplasm originating from the surface ovarian epithelium. "Overall, our data validates previously known ovarian cancer genes, such as ERBB2, and also identified novel potential drivers such as MYNN, PUF60 and TPX2." (PMID 20386695, 2010).
coeliac disease (1 paper, 2021). "As regards coeliac disease diagnosis above 7 years of age in the case–control analysis, rs653178 (at SH2B3/ATXN2), rs13010713 (at ITGA4/UBE2E3), rs13151961 (at IL2/IL21), rs11712165 (at CD80) and rs10936599 (at MYNN) showed an association." (PMID 33446885, 2021).
Obesity (1 paper, 2013). Accumulation of substantial excess body fat. "Eight genes (BCAT1, BMP2 K, CSRNP2, MYNN, NCKAP5L, SAP30BP, SLC35B4, and SP1) were isolated as candidates for obesity." (PMID 24455749, 2013).
ovarian serous adenocarcinoma (1 paper, 2009). An adenocarcinoma that arises from the ovary and is characterized by the presence of malignant epithelial cells that, in well differentiated tumors, resemble the epithelium of the fallopian tube or, in poorly differentiated tumors, show anaplastic features and marked nuclear atypia. "The LCM data set shows over-expression of CLDN11, MYNN, PRKCI, and SKIL in ovarian serous adenocarcinoma." (PMID 19419571, 2009).
cancer (3 papers, 2010 to 2024). A tumor composed of atypical neoplastic, often pleomorphic cells that invade other tissues. "Single nucleotide polymorphism of MYNN, rs109365 has an impact on the telomere length, gene expression, developmental processes, and several cancer development processes." (PMID 38165846, 2024). "In summary, in silico comprehensive characterization of coding and non-coding single nucleotide polymorphisms of MYNN gene will assist researchers to work on MYNN gene and establish their association with certain types of cancers." (PMID 38165846, 2024). "MYNN gene encodes myoneurin protein, which has been associated with several cancer pathogenesis and disease development processes." (PMID 38165846, 2024). "While the role of MYNN in cancer is yet to be characterised, other members of this family are similarly overexpressed in tumors." (PMID 20386695, 2010). "Some of the transcription factors that were specifically expressed in OS-DW cells were ATF6, CDX2, FOSL1, PRDX3, FZD6, MYNN, TRAF1 which are known to regulate pathways implicated in cancers like, Wnt/Hedgehog/Notch signaling, MAPK signaling, Apoptosis and mTOR signaling." (PMID 31690262, 2019).
MYNN also shares sentences with these, for which no sentence is quoted: colorectal cancer (2 papers).